OR8G3 (olfactory receptor family 8 subfamily G member 3 (gene/pseudogene))
Description:
Odorant receptor.
Synonyms: OR8G3P
Gene: Protein-coding gene on chromosome 11 (124,211,707 to 124,215,828, forward strand). Ensembl gene ENSG00000255425.
Subcellular location: Cell membrane
Genetic constraint (gnomAD): Missense variants: 263 observed, 308.73 expected, observed/expected ratio (o/e) 0.85, 90% interval 0.77 to 0.94. Synonymous variants: 110 observed, 113.83 expected, observed/expected ratio (o/e) 0.97, 90% interval 0.83 to 1.13.
Homologues: Orthologues: chimpanzee OR8G3P (87% identical), mouse Or8g2 (82% identical), dog OR8G3 (79% identical), rat Or8g2c (79% identical), mouse Or8g2b (78% identical), tropical clawed frog or5dd2b (43% identical). Paralogues in human: OR8G2P (87% identical), OR8G1 (77% identical), OR8G5 (75% identical), OR8A1 (64% identical), OR8B3 (62% identical), OR8D2 (62% identical), OR8B2 (62% identical), OR8D1 (62% identical), OR8B8 (61% identical), OR8D4 (60% identical), OR8B12 (58% identical), OR8B4 (57% identical), and 84 more.